CCR2 (C-C motif chemokine receptor 2)
Diseases named in the same sentence as CCR2 in open-access papers (continued):
Sharing a sentence is not in itself a finding about the gene and the disease.
Arthritis (continued). "Given the specific proinflammatory role of Th17 cells in autoimmune diseases, we hypothesized that skewing of Th17 cells and Th17-cell responses may account for the exacerbated arthritis in CCR2−/− mice." (PMID 21991368, 2011). "Our results suggest a previously unrecognized mechanism that CCR2 may be important in maintaining immunological homeostasis and protecting against collagen-induced arthritis via regulation of Th17 cell responses." (PMID 21991368, 2011). "However, more severe arthritis was developed in CCR2−/− mice that were induced by collagen immunization." (PMID 21991368, 2011). "Taken together, our results not only validate the importance of local CCR2 targeting in preventing the structural damage of cartilage and bone following injury but also confirm our polymeric, biodegradable microplates as successful drug carriers for therapeutic purposes in arthritis." (PMID 36109442, 2023). "Altogether, these results identify a promising dual action of CCR2 blockade, acting on both nociceptor sensitization and peripheral inflammation, that could lead to the development of more adequate pharmacological agents to manage chronic painful arthritis." (PMID 33757529, 2021). "We propose that addition of CCR2 blocking to standard treatment, i.e., DMARDs, early in the course of arthritis may significantly improve disease outcome by suppressing infiltration of circulatory OCPs and, thus, reduce the number of active bone-resorbing osteoclasts." (PMID 34925336, 2021). "Analysis of adjuvant-induced arthritis(AIA) in IL6+/+ and IL6−/− mice demonstrated that IL6 deficiency is associated with reduced synovial infiltration and is accompanied by a defect in both CCL2 expression and the recruitment of leukocytes bearing the CCL2 receptor CCR2." (PMID 33126846, 2020). "We have previously shown that delivery of GMME1 via a gene-enhanced cellular platform to mice ill with EAE or arthritis, led to immune suppression and clinical remission and we here found that the same platform could serve to treat mice implanted with CCR2+ EG7 lymphoma." (PMID 21943176, 2011). "Blockade of CCR2 in collagen-induced arthritis produced varying results, with the effect being critically dependent on the timing of blockade, suggesting that in the late phase of disease, other populations of cells, perhaps with a regulatory function, may express CCR2." (PMID 16507178, 2006). "Consequently, intervention with an antibody to CD200 polarized CD2+MHC-II+CCR2+ myeloid precursors toward a proinflammatory phenotype in vitro and allowed the in vivo spreading of psoriatic disease from the skin to the joints even in initially arthritis-resistant mice." (PMID 41482544, 2026). "Rather, the local microenvironment, particularly CD200+ fibroblasts, acted as gatekeepers of arthritis, engaging the checkpoint receptor CD200R1 on migrating CD2+MHC-II+CCR2+ myeloid precursors." (PMID 41482544, 2026). "Consistent with our previous observations in mice and humans, we observed an increase in CD2+MHC-II+CCR2+ myeloid precursors and a significant decrease in CD200+ fibroblasts in the synovial tissue during the onset of arthritis in humans." (PMID 41482544, 2026). "The aim of our study was to identify differentially expressed genes as indicators of a transcriptional response to arthritis in two OCP subsets, defined by the level of CCR2 expression." (PMID 36591261, 2022). "B cells from the SF of arthritis patients showed a significant increase in the surface expression of CCR1, CCR2, CCR4, CCR5 and CXCR4 with respect to PB." (PMID 29880013, 2018). "Especially, CCR1, CCR2 and CCR5 are abundantly expressed on RA synovial macrophages and the validity of CCR1, CCR2 and CCR5 antagonist for the animal model of arthritis has been studied." (PMID 25248373, 2014).
Arthritis (continued). "After blocking CD200, initially arthritis-resistant animals developed joint inflammation on day 21, supporting the critical gate-keeping role of CD200+ fibroblasts interacting with migrating CD2+MHC-II+CCR2+ myeloid precursors." (PMID 41482544, 2026). "Additionally, other studies have shown that the expression of CCR1, CCR2, CCR4, CCR5, and CXCR4 on the surface of B cells in synovial fluid (SF) of arthritis patients is significantly increased." (PMID 41481752, 2026). "Several studies have demonstrated a correlation between CCR2 and Th17 cells, revealing that mice lacking CCR2 exhibit exacerbated collagen-induced arthritis due to increased Th17 cell activity and elevated levels of IL-17A, IL-6, and IL-1β." (PMID 39903705, 2025). "The largest arthritis-induced increase was observed for CCR2, CCR5, and CX3CR1 expressing OCP subsets, but due to their sufficient expression in both (ctrl and CIA) groups, we selected CCR2 and CX3CR1 for further investigation." (PMID 34925336, 2021). "Likewise, in preclinical models of arthritis, both CCL2 and CCR2 were found to be upregulated in joints and peripheral tissues and to drive monocyte/macrophage recruitment and inflammation." (PMID 33757529, 2021). "OCPs from patients with arthritis had higher expression of CCR1, CCR2, CCR4, CXCR3, and CXCR4." (PMID 28619088, 2017). "This antibody has been used to specifically target CCR2+ monocyte subsets in models of toxoplasmosis, arthritis and gram negative bacterial meningitis." (PMID 25884830, 2015). "It was reported that deficiency of CCR9, as well as CCR1, CCR2 and CCR5, did not attenuate a murine model of serum transfer arthritis." (PMID 25248373, 2014). "Consistently, levels of IL-17A, but not IFN-γ in the serum of CCR2−/− mice were significantly increased in the early phase of arthritis." (PMID 21991368, 2011). "Notably, when GFP+ γδ T cells were gated, CCR2 was expressed at similar levels even in cells from anti-CCL2 mAb-treated non-arthritic mouse joints, suggesting that CCR2 expression in γδ17 cells is required for the development of arthritis." (PMID 26108163, 2015). "However, mice lacking CCR2 develop exacerbated collagen-induced arthritis." (PMID 21991368, 2011). "We then used imaging mass cytometry (IMC) to detect CD2+MHC-II+CCR2+ myeloid precursors and CD200+ (DKK3+FAP+CD45−CD31−) fibroblasts in the synovial tissues of individuals with early PsA who had just developed arthritis and individuals with psoriasis without arthritis." (PMID 41482544, 2026).
diabetes (34 papers, 2012 to 2025). "By encouraging the recruitment of monocytes and macrophages to inflammatory sites, CCR2 regulates the immune response and is linked to the development of diabetes." (PMID 39125901, 2024). "In a genetic model of diabetes, reduced CD11bhighF4/80low macrophage recruitment via CCR2 antagonist was associated with protection from kidney damage." (PMID 30456449, 2019). "Previous studies indicated a relation between CCR2V64Il, a variant of CCR2, and some inflammatory and autoimmune diseases such as coronary artery disease, diabetes mellitus, progression of HIV, chronic renal failure, and trigeminal neuralgia." (PMID 24453913, 2013). "The aim of this study was to determine the role of CCR2+ inflammatory monocytes in the pathogenesis of diabetes-induced degeneration of retinal capillaries." (PMID 36698021, 2023). "In this study, we used ERG, spatial frequency threshold and contrast sensitivity to investigate the role of CCR2+ monocytes in diabetes-induced visual dysfunction." (PMID 36698021, 2023). "Additional studies will be required to determine if more potent inhibitors of CCR2 offer meaningful clinical benefit to patients with diabetes." (PMID 36698021, 2023). "The beneficial effect of a CCR2/5 inhibitor on vascular permeability in rodent models of diabetes has been reported previously." (PMID 36698021, 2023). "CCR2 antagonists are under clinical investigation for other indications, for instance, in kidney disease in diabetes." (PMID 35327464, 2022). "For example, in the amelioration of diabetes, miR-129-3p decreases the apoptosis and recruitment of neutrophils by regulating the translation of Casp6 and Ccr2, whereas miR-129-5p inhibits ECM degradation by inhibiting the expression of Sp1-mediated MMP9." (PMID 34777000, 2021). "A meta-analysis of the diabetic patient gene expression profiles has demonstrated that CCR2 may be a promising biomarker for diabetes mellitus and diabetic peripheral neuropathy, but more research is needed on this topic." (PMID 39457105, 2024). "Approaches including targeting the chemokine receptor CCR2 or enhancing heme oxygenase-1 (downstream of Nrf2) favor macrophage polarization towards an M2-like state, mitigating oxidative stress, remodeling, and dysfunction induced by diabetes." (PMID 38774880, 2024). "Although data from others and us indicates that CCR2 is expressed predominantly on monocytes, we immuno-isolated monocytes to directly evaluate the effect of CCR2+ monocytes on endothelial cell cytotoxicity in diabetes." (PMID 36698021, 2023). "Genetic deletion or inhibition of the receptor CCR2 (for a key mediator in the recruitment of inflammatory monocyte chemokine MCP-1) prevented the development of myocardial fibrosis in a model of streptozotocin-induced diabetes." (PMID 37504566, 2023). "OCT analysis after 2 months of diabetes (4–5 months of age) indicated that neither diabetes nor the deletion of Ccr2 caused a significant increase or decrease of outer nuclear layer (ONL) thickness." (PMID 36698021, 2023). "In order to further investigate if diabetes-induced leucostasis and leucocyte-mediated endothelial cell death could be attributed to CCR2+ monocytes, we immuno-isolated monocytes from bone marrow using magnetic bead depletion." (PMID 36698021, 2023). "However, the role of monocytes has yet to be fully investigated; therefore, we used Ccr2−/− mice to study the role of CCR2+ inflammatory monocytes in the pathogenesis of diabetes-induced degeneration of retinal capillaries." (PMID 36698021, 2023). "We suggest that CCR2 inhibitor may ameliorate hepatic steatosis by reducing ER stress and inflammation in type 2 diabetes mellitus." (PMID 25816097, 2015). "To observe whether CCR2 inhibitor affects diabetes-induced hepatic inflammatory responses, we compared the infiltration of hepatic macrophages in the liver." (PMID 25816097, 2015).
diabetes (continued). "C-C chemokine receptor 2 (CCR2) inhibitor has been reported to improve inflammation and glucose intolerance in diabetes, but its mechanisms remained unknown in hepatic steatosis." (PMID 25816097, 2015). "During patient recruitment, we have excluded the possible confounders that could influence the CCR2 expression such as ischemic heart disease, hypertension, diabetes, hyperlipidemia, cerebrovascular disease or renal disease." (PMID 25411969, 2014). "Other than the small sample size of this pilot study, this observation may be explained by the fact that, although the standard dose of PG used for adult patients with chronic hepatitis B is generally 30 mg/d,14 this dose may be insufficient to inhibit CCR2 in the context of diabetes in humans." (PMID 32704573, 2020). "Therefore, Treg-specific CCR2 agonism might be a therapeutic strategy for the treatment of liver damage in diabetes." (PMID 27464894, 2016). "However, these chemokine receptors are responsible for the recruitment of both diabetogenic and protective cells as revealed by the reduced incidence of diabetes observed in the CCR2−/− NOD mice and the accelerated incidence in the CXCR3−/− or the CCR5−/− NOD mice." (PMID 24968718, 2014). "MCP-1, being an overall chemotactic factor, recruits macrophages for immune responses, which along with its receptors (such as CCR2, ACKR1, and ACKR2), significantly impact diseases across different systems like cancer and diabetes." (PMID 39654886, 2024). "Diabetes-induced retinal superoxide, expression of proinflammatory genes Inos and Icam1, leucostasis and leucocyte-mediated cytotoxicity against retinal endothelial cells were inhibited in diabetic Ccr2-deficient mice and in chimeric mice lacking Ccr2 only from myeloid cells." (PMID 36698021, 2023). "In our study, incidences of diabetes and heart failure were higher and LVEF was lower in patients with enlarged LA compared with normal LA group, indicating that these factors might be directly or indirectly associated with enhanced CCR2 levels and migratory activity in circulating monocytes." (PMID 33048984, 2020). "The diabetes-induced retinal capillary degeneration was inhibited in Ccr2−/− mice and in chimeric mice lacking Ccr2 only from myeloid cells." (PMID 36698021, 2023). "In vivo examination of mice by high-resolution SD-OCT was used to determine the effect of diabetes and the absence of Ccr2 on retinal structure and thickness." (PMID 36698021, 2023). "Since retinal capillary degeneration in diabetic Ccr2−/− mice was significantly higher than that in nondiabetic Ccr2−/− mice, however, the data suggest that CCR2+ monocytes are not the only determinants of retinal capillary degeneration in diabetes." (PMID 36698021, 2023). "Characterized by chronic low-grade inflammation, diabetes alters the expression of key inflammatory mediators such as monocyte chemoattractant protein-1 (MCP-1), interleukin-6 (IL-6), and C-C motif chemokine receptor 2 (CCR2), which collectively modulate peripheral and central immune responses." (PMID 40831951, 2025). "Compared with that in control mice, CCR2 expression in epididymal adipose tissue from diet-induced obese mice fed a high-fat diet for 24 weeks is elevated, and treatment with pioglitazone, which is used to treat diabetes, results in lower CCR2 expression in comparison to obese nontreated mice." (PMID 39457105, 2024). "Although CCR2 is expressed in myeloid cells in nondiabetic animals, it is conceivable that diabetes might result in induction of the receptor elsewhere." (PMID 36698021, 2023).
Sepsis (34 papers, 2011 to 2025). Sepsis is defined as life-threatening organ dysfunction caused by a dysregulated host response to infection. "Sepsis‐trained resident macrophages released a chemokine network including CXCL16 triggers tissue residency of T cells via CCR2 and CXCR6 stimulations responsible for decreased risk of tumor development after sepsis cure." (PMID 39494816, 2024). "A CCR2-deficiency improved the severity of sepsis and a supply of peripheral monocytes restores sepsis in CCR2-deficient mice, suggesting that the existence of monocytes in the periphery enhances systemic inflammation." (PMID 39040105, 2024). "To further demonstrate that the LPS-induced monocyte reduction in the BM was unlikely due to the egress of monocytes from the BM, we induced LPS-induced sepsis in CCR2-deficient mice." (PMID 39040105, 2024). "Neutrophils and CCR2+ inflammatory monocytes are recruited to the brains of both patients and mice suffering from sepsis-associated encephalopathy via increases in chemokine expression and subtle microglial activation, causing persistent cognitive impairment." (PMID 35661951, 2022). "As the decrease of monocytes in the BM was observed even in CCR2-deficient mice 12 hours after LPS treatment, the egress of monocytes from the BM seems not to be a cause of the monocyte reduction in the BM at the early stage of sepsis." (PMID 39040105, 2024). "Data from mice with sepsis-associated encephalopathy, an established model of delirium, demonstrated reduced neuroinflammation accompanied with reduced signs of cognitive impairment by prevention of CCR2 + monocyte recruitment." (PMID 31969629, 2020). "In contrast to the lack of CXCR2 function that impacts neutrophil function during sepsis, the effects of CCR2 were associated with increased function, demonstrated by the finding that severity of patient illness correlated positively with increasing neutrophil chemotaxis to CCR2 ligands." (PMID 30931316, 2019). "Our study identified CCR2 on CD14 − CD16 + monocytes, as participants in the innate immune response, to be inversely associated with the risk of developing sepsis." (PMID 40797460, 2025). "Sepsis-trained lung macrophages stimulated CCR2 and CXCR6 chemokine release, triggering T-cell tissue residency - an immune mechanism that reduced post-sepsis tumor recurrence risk." (PMID 41403926, 2025). "Our findings suggest that genetically determined increases in certain immune cell phenotypes, such as CCR2 on CD14 − CD16 + monocytes, HLA-DR + natural killer absolute count, and CD3 − lymphocyte %leukocyte, are associated with a reduced risk of sepsis." (PMID 40797460, 2025). "Previously, we have demonstrated that NFATc3 regulates macrophage effector functions by regulating different cytokines, CCR2, and iNOS during sepsis and acute lung injury." (PMID 37523510, 2023). "In a model of S. pneumoniae pneumonia-induced sepsis, intravital imaging of CCR2 reporter mice brain showed an increase in the rolling and adhesion of CCR2+ monocytes in the vasculature." (PMID 35603184, 2022). "To address the mechanism of neutrophil migration to muscle, we examined expression of CXCR2 and CCR2 of neutrophils in muscle after sepsis, which are known as neutrophil migration factors." (PMID 36389802, 2022). "CCR2 has been identified as a receptor that is responsible for the inappropriate recruitment of PMNs to different organs during acute sepsis." (PMID 33791319, 2021). "The relationship between CD64 surface level, CCR2 surface level, NETosis, and sepsis are mediated through the effect of infection." (PMID 33424860, 2020). "CD64 and CCR2 receptors are not constitutively expressed on neutrophils at resting state; however, earlier studies showed that CD64 and CCR2 surface levels were increased during sepsis." (PMID 33424860, 2020). "In this study, genetic, or pharmacologic inhibition of CCR2 protected mice from mortality in a cecal ligation puncture (CLP) sepsis model." (PMID 30931316, 2019).